CRYAB (crystallin alpha B)
Diseases named in the same sentence as CRYAB in open-access papers (continued):
Sharing a sentence is not in itself a finding about the gene and the disease.
cancer (continued). "Numerous studies have reported that ZEB1 contributes to cancer progression, while the role of CRYAB and SQLE in BC is rarely reported." (PMID 34490263, 2021). "Various clinical studies have highlighted that high CRYAB expression is a prognostic biomarker for various human cancers including CRC." (PMID 34069924, 2021). "Further, we confirmed the role of CRYAB in cancer invasion and metastasis through cell and animal experiments, as well as human cancer tissue assessment." (PMID 31097690, 2019). "Until recently, increasing clinical studies have shown that high CRYAB expression is a prognostic biomarker for various human cancers including CRC12–15." (PMID 30082880, 2018). "Notably, autophagy, angiogenesis and, hypoxia have a significant-positive correlation to CRYAB expression across several cancer types such as adenocarcinomas of colon, lung, prostate, and stomach." (PMID 36624493, 2023). "First, this work analyzed CRYAB expression in pan-cancer using the TIMER2.0." (PMID 36713654, 2022). "Studies have shown that CRYAB is involved in cancer migration, chemoresistance, and poor prognosis." (PMID 35333695, 2022). "Altogether, these findings show that CRYAB has complex roles in malignant tumors." (PMID 36713654, 2022). "Alpha B-crystallin (CRYAB), as a small heat shock protein, may play critical roles in the tumorigenesis and progression of several kinds of human cancers." (PMID 33607849, 2021). "The results of UALCAN database analysis showed that the mRNA expression levels of CALR, CREB3L3, FBOX6, and KDELR3 were increased in cancer tissues compared with normal tissues, while the mRNA expression levels of CRYAB, DNAJB4, and HSPB6 were decreased in BLCA." (PMID 34930465, 2021). "Proteomic analysis by the iTRAQ quantitation strategy and GO ontology of the cancer cells indicated that αB-Crystallin (CRYAB) might be involved in this process." (PMID 31097690, 2019). "This can be justified by the role of CRYAB in the tyrosine kinase signaling, that could be easily altered in cancer cells." (PMID 21915251, 2011). "From the proteomics or protein level studies, it has recently been recognized that CRYAB may have a role in cancer development." (PMID 21915251, 2011). "In this study, we identified a set of associated DEGs (CD44, CTGF, DPP4, CRYAB, EGLN3, FGF1, and FOS) with at least one functional enrichment, such as “angiogenesis”, “binding of endothelial cells”, “development of blood vessel”, MAPK signaling, HCM, and pathways in cancer." (PMID 28623314, 2017). "The αB-crystallin (HSPB5, CRYAB, CRYA2, or MFM2) is a ubiquitous chaperone involved in the development of neurological diseases, certain myopathies, and cancers." (PMID 36765939, 2023). "In our eight signature genes (ARL6IP4, ATP2A1, CRYAB, ELFN2, MAP2, MAT1A, ORC1, and POU4F1), prior research has elucidated the expression and function of several genes involved in the initiation and progression of cancer." (PMID 41567198, 2025). "Besides, we found that CRYAB was negatively related to TMB and MSI in some cancers, such as LUAD, PRAD, BLCA, ESCA, PAAD, STAD, SARC, and LGG." (PMID 36713654, 2022). "CRYAB expression in COAD was similar to that in OV and high expression of CRYAB positively correlated with high-grade malignancies, more advanced tumors, lymph nodes, metastatic (TNM) cancer stages, and poor survival outcomes." (PMID 36713654, 2022). "CRYAB, a member of the small heat shock protein family, could regulate several signaling pathways including PI3K/AKT and ERK pathways in cancers." (PMID 33519933, 2021). "It is also appreciated that the same chaperone can be associated with both good and poor patient survival depending on the cancer type demonstrating that context is key, but for HSP27, like CRYAB, that context remains unclear." (PMID 35235182, 2021).
cancer (continued). "Based on TCGA BLCA dataset, we found that CRYAB (AUC = 0.9326, P < 0.001), ECM1 (AUC = 0.6782, P = 0.009), CGNL1 (AUC = 0.9314, P < 0.001), and GPX3 (AUC = 0.8480, P < 0.001) are effective in distinguishing HGBC tissues and normal para-carcinoma tissues." (PMID 32292720, 2020). "On the contrary, negative LASSO coefficients were found for the genes ADRB2, CRYAB, NR4A1, CMTM5, ZBTB16, SYNE3, and RAD51, which were downregulated in cancer compared with normal samples." (PMID 36552262, 2022). "Besides, we analyzed the CRYAB total protein expression in cancers via CPTAC and found that, unlike normal tissues, CRYAB protein expression levels were significantly low in COAD, HNSC, PAAD, OV, UCEC, LUAD, and liver hepatocellular carcinoma (LIHC) except for KIRC." (PMID 36713654, 2022).
myopathies (23 papers, 2012 to 2025). "CRYAB, a sarcoplasmic chaperone, was previously implicated in myofibrillar myopathies and desmin-related myopathy (DRM), a neuromuscular disease characterized by protein aggregates in muscle cells." (PMID 37371072, 2023). "Decades ago, a genetic linkage study identified a novel variant of the alpha-crystallin B chain (CRYAB) as a cause of HCM in a French family with myopathy in multiple organs." (PMID 37435054, 2023). "Mutations in CryAB, specifically the dominant R120G mutations in the CryAB gene (CryABR120G), lead to myopathies via reductive stress, which is responsible for cellular hypertrophy in cardiomyocytes derived from induced pluripotent stem cells." (PMID 32566086, 2020). "HSPB5 (alpha-B crystallin, CRYAB) mutations can cause myopathy with myofibrillar pathology or CMT2." (PMID 40243504, 2025). "The reported pathological features in all HSPB8-related myopathies have been similar: dystrophic changes and MFM pathology with protein aggregates (desmin, myotilin, CRYAB, dystrophin, HSPB8, DNAJB6, myotilin, BAG3, TDP-43, and ubiquitin) and rimmed vacuoles." (PMID 32093037, 2020). "Furthermore, crystallin alpha B does not show any change during age-related cataract (columns 8 and 7), which is consistent with the fact that it has been shown to cause myopathy through other effects." (PMID 23244575, 2012). "In line with human patients with HSPB8-related myopathy, the muscle pathology shows features of human myofibrillar myopathy, with Z-disc disintegration, accumulation of granulofilamentous material, aggregates positive for HSPB8, CRYAB, and desmin, and rimmed vacuoles." (PMID 32093037, 2020). "The linkage intervals included the myopathy genes MYOT and CRYAB, but neither of these contained coding or splice site mutations by Sanger sequencing." (PMID 22371254, 2012).
neurodegenerative disease (12 papers, 2014 to 2026). A disorder of the central nervous system characterized by gradual and progressive loss of neural tissue and neurologic function. "Increased expressions of Crystallin Alpha B (Cryab) and apolipoprotein E (ApoE) have been associated with protective reactive gliosis in neurodegenerative diseases such as Parkinson’s disease (PD), Alzheimer’s disease (AD), and Multiple Sclerosis (MS)." (PMID 36457352, 2022). "The expression of CRYAB may be regulated by inflammatory cytokines and, in turn, can influence the extent and progression of the inflammatory response.In the nervous system, abnormal expression of the CRYAB gene is associated with the occurrence and progression of several neurodegenerative diseases." (PMID 38274814, 2023). "Chaperones HSPB5 (also known as CRYAB) and HSPB1/HSP27 are overexpressed in neurodegenerative diseases and these heat shock proteins are conservative among different species." (PMID 34572572, 2021).
cardiac disease (6 papers, 2009 to 2025). "We show that MLF2, identified in protein aggregates across cardiac and non-cardiac disease models, interacts with proteins involved in proteostasis, including CryAB." (PMID 41590846, 2025). "Previous studies have established CRYAB’s involvement in structural heart diseases; however, our data provide strong support for its role in electrical dysfunction as well." (PMID 41153379, 2025). "The screened hub genes, PIK3R1, SPNB2, and CRYAB, have been validated as credible molecular biomarkers using the mouse MI model and human blood samples, which may provide a novel therapy for cardiac diseases with increased proteotoxic stress." (PMID 34887920, 2021). "Importantly, this analysis highlighted new potential dystrophin-associated proteins that were specific to cardiac DYS-IPs and involved proteins with known associations to cardiac disease in humans: Cavin-1 (PTRF), Ahnak1 (desmoyokin), Cypher (LDB3, ZASP), and Crystallin alpha B (CRYAB)." (PMID 22937058, 2012).
infection (4 papers, 2017 to 2023). The state of being infected such as from the introduction of a foreign agent such as serum, vaccine, antigenic substance or organism. "Western blot analysis of CVB3-infected mouse heart also revealed enhanced phosphorylation of CryAB at day 3 and 9 post-infection." (PMID 29088822, 2017). "We further demonstrated that CryAB was phosphorylated during early and downregulated at later stages of infection." (PMID 29088822, 2017).
neuromuscular disease (3 papers, 2020 to 2023). "In this review, we cover mutations in DNAJB6, DNAJB2, αB-crystallin (CRYAB, HSPB5), HSPB1, HSPB3, HSPB8, and BAG3, and discuss the molecular mechanisms by which they cause neuromuscular disease." (PMID 32093037, 2020). "Of the 10 sHSPs (or HSPBs) encoded by the human genome, four are currently known to be associated with neuromuscular disease; these are HSPB1 (Hsp27), HSPB3, αB-crystallin (CRYAB, HSPB5), and HSPB8 (Hsp22)." (PMID 32093037, 2020).
CNS tumors (1 paper, 2023). "The CRYAB protein was found to be controversial, as our results showed a positive association with invasion, but in HPA, high tissue expression was associated with a better prognosis in CNS tumors." (PMID 37986165, 2023).
kidney diseases (1 paper, 2023). "Based on the known functions of the DKD candidate marker genes, it appears that many associate with kidney diseases, and our stress score genes, particularly GPX3, HRSP12, MSRA, MSRB1, and CRYAB, protect the cell and/or cellular proteins during stress." (PMID 37216114, 2023).
prostate (1 paper, 2013). "Among them, CRYAB, KCNMA1 and SDPR were overexpressed in all 3 reference tissues and could be considered as genes protective against PCa and therefore involved in the early stages of prostate carcinogenesis." (PMID 23840433, 2013).
Retinopathy (1 paper, 2023). "Retinopathy progression co-occurred with the enhancement of p38 MAPK-dependent phosphorylation of CryaB at Ser59 in the retina." (PMID 37511345, 2023).
CRYAB also shares sentences with these, for which no sentence is quoted: hepatocellular carcinoma (5 papers); idiopathic pulmonary fibrosis (5); colon cancer (3); distal hereditary motor neuropathy (3); head and neck squamous cell carcinoma (3); muscular disease (3); relapsing-remitting MS (3); tauopathy (3); acute myocardial infarction (2); amyloidosis (2); amyotrophic lateral sclerosis (2); cystic fibrosis (2); diabetic retinopathy (2); experimental autoimmune encephalomyelitis (2); inflammation (2); laryngeal squamous cell carcinoma (2); muscular dystrophy (2); Myocardial fibrosis (2); myocardial ischemia (2); neurological diseases (2); neuropathies (2); renal cell carcinoma (2); rheumatoid arthritis (2); sarcoma (2); thyroid cancer (2); acute myeloid leukemia (1); adenocarcinoma (1); Age-related nuclear cataract (1); Alexander disease (1); alphaB-crystallinopathy (1).
A further 63 diseases each share a sentence with CRYAB in 1 paper.